SIRT5 (sirtuin 5)
Diseases named in the same sentence as SIRT5 in open-access papers (continued):
Sharing a sentence is not in itself a finding about the gene and the disease.
hepatocellular carcinoma (33 papers, 2017 to 2026). A malignant tumor that arises from hepatocytes. "A SIRT5 deficiency in hepatocellular carcinoma (HCC) increases oxidative DNA damage by elevating ACOX1-mediated H2O2 production." (PMID 33117804, 2020). "In hepatocellular carcinoma (HCC), SIRT5 deficiency leads to increased succinylation and activity of Acyl-CoA Oxidase 1 (ACOX1), which is directly associated with oxidative stress and DNA damage responses in HCC." (PMID 40463370, 2025). "Recent studies have shown that the role of SIRT5 in the development of renal cell carcinoma, breast cancer, and hepatocellular carcinoma depends on its deacetylase activity." (PMID 40557149, 2025). "Some studies have shown that ACOX1 activity increasing due to SIRT5 expression downregulated in primary hepatocellular carcinoma cancer results in poor HCC survival." (PMID 37724116, 2023). "In previous studies SIRT5 has been found downregulated in different cancers like liver cancer gastric cancer and hepatocellular carcinoma." (PMID 36809279, 2023). "Hypoxia-induced miR-3677-3p promotes the proliferation, migration, and invasion of hepatoma cells by inhibiting SIRT5." (PMID 36090902, 2022). "SIRT5 expression is higher in hepatocellular carcinoma cell lines than in normal hepatocyte cell lines, and SIRT5 overexpression promotes hepatocellular carcinoma cell proliferation, but knockdown of SIRT5 inhibits hepatocellular carcinoma cell proliferation." (PMID 35493297, 2022). "Further, the knockdown of SIRT5 can promote apoptosis in hepatocellular carcinoma cells through the mitochondrial pathway." (PMID 35493297, 2022). "Relevant studies revealed that SIRT5 can promote autophagy of gastric cancer cells, and SIRT5 can inhibit peroxisome-induced oxidative stress, thus protecting the liver and inhibiting the development of hepatoma cells." (PMID 36172179, 2022). "Whether SIRT5 regulates CS through its de-succinylation activity to exert its suppressive effect in hepatocellular carcinoma remains unclear." (PMID 40557149, 2025). "Targeting SIRT5-mediated de-succinylation of CS may represent a promising therapeutic strategy for the treatment of hepatocellular carcinoma." (PMID 40557149, 2025). "This study suggests that SIRT5-mediated regulation of CS succinylation may serve as a novel therapeutic target for hepatocellular carcinoma." (PMID 40557149, 2025). "Similarly, SIRT5 overexpression enhanced the proliferation of hepatocellular carcinoma cells, while SIRT5 knockdown significantly suppressed their proliferation." (PMID 40218465, 2025). "Specifically, SIRT5 may prevent tumor immune evasion and suppress hepatocellular carcinoma development." (PMID 39201811, 2024). "In hepatocellular carcinoma, SIRT5 can inhibit cell apoptosis by deacetylating cytochrome c." (PMID 31817470, 2019). "Previous studies have confirmed that SLC25A51 is significantly overexpressed in human hepatocellular carcinoma (HCC) and enhances glycolysis and HCC progression by activating sirtuin 5 (SIRT5)." (PMID 36902385, 2023). "For instance, SIRT5 mediates the desuccinylation of ACOX1, decreasing its activity in hepatocellular carcinoma development." (PMID 40243486, 2025). "We recently reported that low SIRT5 expression is associated with unfavorable prognosis for hepatocellular carcinoma cancer (HCC) patients, although whether SIRT5 downregulation contributes to HCC development remains to be addressed." (PMID 30759120, 2019). "In addition, SIRT5 desuccinylation inhibits hepatocellular carcinoma (HCC)." (PMID 39979670, 2025). "In hepatocellular carcinoma (HCC), SIRT5 also exerts a tumor-suppressive function." (PMID 39944690, 2025). "In addition, SIRT5 regulates the activity of ACOX1 to counteract oxidative stress and is expressed less in hepatocellular carcinoma." (PMID 38585644, 2024).
hepatocellular carcinoma (continued). "Most importantly, vimentin undergoes various functionally important PTMs, including acetylation, and one sirtuin family member, SIRT5, was found to physically interact with and deacetylate vimentin at K120 and thus influence the EMT process in hepatocellular carcinoma cells." (PMID 34605151, 2021).
colorectal cancer (27 papers, 2018 to 2025). A primary or metastatic malignant neoplasm that affects the colon or rectum. "Accordingly, the level of SIRT5 is associated with overall survival of patients with colorectal cancer, suggesting an oncogenic role for this protein." (PMID 31947673, 2020). "Another interesting study showed that sirtuin 5 (SIRT5) promotes glutamine anabolic metabolism and is associated with colorectal cancer cell proliferation, survival, and xenograft tumor growth." (PMID 31947673, 2020). "SIRT5 is a key modulator of the response to starvation, metabolic homeostasis and cellular survival promoting autophagy in colorectal cancer and its overexpression in this cancer is associated with poor survival." (PMID 31608237, 2019). "Sirtuin 5 (SIRT5) has been associated to colorectal cancer and metabolic regulation." (PMID 36253417, 2022). "SIRT5 has been reported to inhibit T‐cell activation in colorectal cancer, particularly regulating the differentiation of Treg and Th1 cells." (PMID 40672112, 2025). "For instance, SIRT5 expression promotes colorectal cancer cell survival by stimulating autophagy through the deacetylation of lactate dehydrogenase B, which facilitates lysosomal acidification." (PMID 41304967, 2025). "This conclusion is consistent with the inhibition of colorectal cancer by SIRT5 modulator mentioned earlier." (PMID 39979670, 2025). "In mouse xenograft models, colorectal cancer cells with enhanced SIRT5-transketolase signaling exhibited accelerated tumor growth." (PMID 41304967, 2025). "Previous studies have found that SIRT5 is highly expressed in colorectal cancer (CRC), and knockdown of SIRT5 impairs the production of ribo-5-phosphate, which is required for nucleotide synthesis, resulting in continuous and irreparable DNA damage." (PMID 40260239, 2025). "In colorectal cancer, SIRT5 (resveratrol and sulforaphane) acts on the chemotherapeutic drug 5-FU, affecting the proliferation of cancer cells." (PMID 39479446, 2024). "In contrast, in the colorectal cancer cells, the sirtuin 5 knockout and ensuing TKT malonylation inhibit the PPP-dependent production of ribose-5-phosphate in the non-oxidative branch of PPP." (PMID 38255994, 2024). "SIRT5 deacetylates lactate dehydrogenase B (LDHB) and promotes its enzymatic activity, thus generating additional protons and increasing autophagy and tumorigenesis in colorectal cancer, and the knockdown of SIRT5 reduces cancer cell proliferation." (PMID 36010594, 2022). "Here, the authors show that SIRT5 silencing reduces nucleotide availability leading to DNA damage and tumor suppression in colorectal cancer models." (PMID 36253417, 2022). "In HCT-116 colorectal cancer cells, SIRT5 removes succinyl groups from K393 and K395 of citrate synthase." (PMID 34650436, 2021). "In particular, SIRT5 silencing induces apoptosis and cell cycle arrest in colorectal cancer cells, while its overexpression promotes tumor growth in mouse xenograft models." (PMID 31947673, 2020). "SIRT5 was overexpressed in non-small cell lung cancer and colorectal cancer, high SIRT5 expression was an unfavorable predictor of survival." (PMID 32158696, 2020). "Recently, it has been reported that SIRT5 overexpresses in colorectal cancer tissues and plays a part in glutamine metabolic rewiring." (PMID 32953892, 2020).
colorectal cancer (continued). "Here we show that mitochondrial Sirtuin5 (SIRT5), which mediates lysine desuccinylation, deglutarylation, and demalonylation, plays a role in colorectal cancer (CRC) glutamine metabolic rewiring." (PMID 29416026, 2018). "Overexpressing SIRT5 leads to a poor prognosis for colorectal cancer patients." (PMID 41304967, 2025). "Consequently, inhibition of demalonylase activity of SIRT5 is a potential therapeutic pathway for colorectal cancer." (PMID 39979670, 2025). "For example, sirtuin 5 (SIRT5) can deacetylate LDHB at lysine 329 to accelerate the growth of colorectal cancer, and the increased phosphorylation of LDHB at serine 162 can promote NAD+ regeneration, glycolytic flux, lactate production, and glycolytic intermediate generation." (PMID 36612084, 2022). "The SIRT5 (sirtuin 5) gene could have large impact on cellular homeostasis and is more expressed in colorectal cancer." (PMID 35976909, 2022). "However, it was also reported that SIRT5-positive colorectal cancer cells with wild-type KRAS were resistant to either chemotherapeutic agents or cetuximab; SIRT5 promoted cisplatin resistance in ovarian cancer." (PMID 33516270, 2021). "We therefore investigated whether inflammatory cytokines might play a role in mediating the progression of colorectal cancer through SIRT5." (PMID 32953892, 2020). "Additionally, SIRT5 acts as a deacetylase, desuccinylase, and a demalonylase to activate target proteins such as lactate dehydrogenase B, and transketolase, promoting cell proliferation, oxidative stress, and cell survival in colorectal cancer." (PMID 41304967, 2025). "SIRT5 can mediate the deacetylation of lactate dehydrogenase B (LDHB) thus promoting autophagy and tumorigenesis in colorectal cancer." (PMID 39479446, 2024). "SIRT5 was also found to modulate the deacetylation of LDHB and induce the autophagy in colorectal cancer." (PMID 35136826, 2022). "SIRT5 can not only demalonylate and inactivate SDHA to cause multidrug resistance in wild-type Kras colorectal carcinomas (CRCs) but also mediate TPI demalonylation and impair its formation and activity, causing recurrence of mutant Kras CRC." (PMID 35428309, 2022). "SIRT5 also activates LDHB, which induces autophagy and cell proliferation of HCT-116 colorectal cancer cells." (PMID 34650436, 2021). "SIRT5 deglutarylates glutamate dehydrogenase 1 (GLUD l) at K545 site and activates its activity, promotes glutamine synthesis and TCA cycling, and promotes colorectal cancer cell growth and proliferation." (PMID 39979670, 2025). "A previous study reports that there is no change in LDHA activity in the SIRT5-KO cells of colorectal cancer." (PMID 35278714, 2023). "Since the succinylation levels of LDHA did not increase in colorectal cancer, it is speculated that the expression of SIRT5 would not affect the change in LDHA activity." (PMID 35278714, 2023). "Contrary, overexpression of sirtuin 5, but not its catalytically inactive mutant, increases the cellular TKT activity in the colorectal cancer cells." (PMID 38255994, 2024). "Another study finds that SIRT5 activates the key enzyme transketolase (TKT) in the non-oxidized pentose phosphate pathway in a demalonylation-dependent manner, maintaining sufficient nucleotide levels for DNA synthesis and promoting colorectal cancer growth." (PMID 39979670, 2025). "In colorectal cancer cells, blocking the sirtuin 5 expression does not affect the expression of TKT but decreases the TKT activity; the decrease is accompanied by impaired availability of ribose-5P for nucleotide synthesis and alleviated by overexpression of TKT in the sirtuin-5-silenced cells." (PMID 38255994, 2024).
gastric cancer (19 papers, 2017 to 2025). A primary or metastatic malignant neoplasm involving the stomach. "Further analysis revealed that the tumor-suppressive effect of SIRT5 in gastric cancer is associated with the regulation of 2-oxoglutarate dehydrogenase (OGDH) expression." (PMID 39944690, 2025). "The authors suggested that SIRT5 suppressed gastric cancer cell growth and migration by inhibiting mitochondrial function and by increasing ROS production via down-regulation of OGDHc activity." (PMID 33946784, 2021). "S100A10 accumulation, which is regulated by the succinyltransferase CPT1A and SIRT5-mediated desuccinylation, promotes gastric cancer cell invasion and migration." (PMID 31739800, 2019). "In contrast, SIRT5 was found to inhibit gastric cancer cell proliferation and tumor formation by inhibiting aerobic glycolysis." (PMID 31456942, 2019). "Beyond these examples, SIRT5 has also been found to inhibit gastric cancer invasion by catalyzing the desuccinylation of S100A10 protein, and it can desuccinylate the K280 site of serine hydroxymethyltransferase 2 (SHMT2) protein, thereby inhibiting osteosarcoma development." (PMID 39944690, 2025). "Functional analyses indicated that overexpression of SIRT5 can inhibit gastric cancer cell growth both in vitro and in vivo by arresting the cell cycle at the G1/S phase and suppressing migration and invasion via modulation of epithelial-mesenchymal transition (EMT)." (PMID 39944690, 2025). "In our study, we found that knocking down SIRT5 in AML cell lines impeded cell viability and promoted apoptosis which was consistent with its functions in gastric cancer cells." (PMID 38585637, 2024). "SIRT5 regulates desuccinylation, and the levels of succinylated S100A10 were increased in human gastric cancer." (PMID 35278714, 2023). "In gastric cancer cell lines, CDK2 modulates the aerobic glycolytic capacity via suppression of SIRT5 which acts as a tumor suppressor in gastric cancer cells." (PMID 36769170, 2023). "Previous studies reported that S100A10 accumulation was involved in gastric cancer cell invasion and migration through the succinyltransferase CPT1A and SIRT5-mediated desuccinylation." (PMID 34178044, 2021). "Thus, both SIRT5 and OGDHc could be novel therapeutic targets for gastric cancer treatment." (PMID 33946784, 2021). "SIRT5-mediated desuccinylation of OGDH inhibits the OGDH complex’s activity, leading to reduced mitochondrial membrane potential, decreased ATP production, increased ROS levels, and altered NADP/NADPH ratios, ultimately suppressing gastric cancer progression." (PMID 39944690, 2025). "Similarly, SIRT5 facilitates the degradation of S100A10 protein, thereby promoting invasive migration in gastric cancer." (PMID 39479446, 2024). "Although SIRT5 plays important regulatory roles in tumor progression in the liver and gastric cancer, the role of SIRT5 in cancer has not been extensively studied compared to other SIRTs." (PMID 35278714, 2023). "In addition to our current results in gastric cancer, previous studies have also shown that ACAT1 expression levels in prostate cancer are higher compared to adjacent normal tissues, with ACAT1 and SIRT5 synergistically promoting the development of invasive prostate cancer." (PMID 39247186, 2024).
lung cancer (16 papers, 2015 to 2025). A malignant neoplasm involving the lung. "For example, SIRT5 knockout (or knockdown) in lung cancer cells led to increased malonylation of glycolytic enzymes and significantly reduced tumor growth both in vitro and in vivo." (PMID 41107644, 2025). "Another study, conducted in lung cancer cells, indicated that SIRT5 inhibits PKM2 through desuccinylation of K498 during oxidative stress, thus impairing glycolysis." (PMID 39215785, 2025). "SIRT5 inhibition hinders the proliferation of lung cancer cells through desuccinylation at this site." (PMID 36397343, 2022). "For example, it has been demonstrated that the Sirt5 mRNA and protein expression levels are frequently elevated in human lung cancers." (PMID 33455080, 2021). "SIRT5 promotes the growth of human non‐small cell lung cancer, and patients with high SIRT5 expression have a poor prognosis." (PMID 33103371, 2020). "While Sirt5 was found to be overexpressed in human non–small cell lung cancer, Sirt5 levels were considerably downregulated in head and neck squamous cell carcinoma." (PMID 32698385, 2020). "We also show that the down-regulation of SUN2 is at least partly mediated by class III of the sirtuin family member SIRT5 in lung cancer." (PMID 26658802, 2015). "We also reported that SIRT5 is at least partly responsible for the down-regulation of SUN2 in lung cancer cells." (PMID 26658802, 2015). "Notably, in HCC,175, 176, 177 breast, prostate, and lung cancer, SIRT5 showed contrasting roles, either supporting or repressing tumor development, suggesting that its function is related to both tissue type and disease stage." (PMID 39215785, 2025). "Furthermore, SIRT5-catalyzed removal of GAPDH malonylation enhances its enzymatic activity, while SIRT5 KO reduces lung cancer cell growth in vitro and in vivo." (PMID 36818560, 2023). "This novel SIRT5/SUN2 axis may be valuable for developing new strategies for treating patients with lung cancer." (PMID 26658802, 2015). "This novel SIRT5/SUN2 axis may be useful for the development of new strategies for treating patients with lung cancer." (PMID 26658802, 2015). "SIRT5 may also play a tumor-promoting function in lung cancer viadifferent mechanisms." (PMID 35802779, 2022). "SIRT5 may alsoplay a tumor-promoting role in lung cancer via inhibitingPKM2." (PMID 35802779, 2022). "Compound 7 was alsotested in A549 lung cancer cells, where it seemed to increase theactivity of PKM2, an enzyme inhibited by SIRT5-mediated desuccinylation,and lead to the suppression of cancer cell proliferation." (PMID 35802779, 2022). "The development of SIRT5 inhibitors (for example, NRD167) now provides a tool to intentionally increase malonylation in tumors, and early results in both leukemia and solid tumors (such as lung cancer) are promising." (PMID 41107644, 2025). "However, we did not observe similar correlation between the protein expression of SIRT5 and SUCLG2, like that between TRIM21 and SUCLG2, in lung cancer tissues and adjacent normal tissues." (PMID 37904651, 2023). "Moreover, SIRT5 was determined to have a partial inhibitory effect on the tumor suppressor SUN2, which was found to increase the sensitivity of lung cancer to cisplatin by inducing apoptosis." (PMID 31456942, 2019).